TNF (tumor necrosis factor)
Diseases named in the same sentence as TNF in open-access papers (continued):
Sharing a sentence is not in itself a finding about the gene and the disease.
tumor (continued). "TNF-α and Il-1β are significant regulators of host defense against tumor cells." (PMID 24348858, 2014). "TNF-α is an important host defence molecule that affects tumor cells." (PMID 25075740, 2014). "Almost identical, a reduction of clonogenicity was detectable in five out of the six tested tumor cell lines after treatment with TNF/zVAD/CHX, with three cell lines showing a statistically significant reduction (KNS-62 cells were only slightly above the significance threshold with P = 0.057)." (PMID 24507727, 2014). "In addition, CTL-derived cytokines, including tumor necrosis factor α, interleukin 4 (IL-4) and IL-10, contribute to tumor rejection by inhibition of tumor stroma formation." (PMID 25289108, 2014). "Despite the name and history of this cytokine, these properties make TNF-α a promoter of inflammation, angiogenesis and tumour dissemination; it could be considered as a tumour-promoting factor." (PMID 26019577, 2014). "This suggests that tumor-derived TNF-α exerts a profound effect on migration and invasion." (PMID 24676340, 2014). "Moreover, expression of both TNF-α and NF-κB was correlated with tumor size, tumor grade, and TNM stage." (PMID 24864130, 2014). "Dwarfing the p75 receptor signaling pathways affects survival and function of both ECs and tumor cells, while continuous increasing levels of TNF in tumor tissue also have a “self-destructive” effect via signaling through the remaining cytotoxic TNFR1/p55 pathways." (PMID 24664144, 2014). "However, when WT-Ras-expressing tumor cells were stimulated by TNFα, cooperativity between the two pathways was obtained." (PMID 24598028, 2014). "However, side effects such as increasing frequency of infection and promoting tumor growth by induction of T cell apoptosis make anti-TNF-α treatment a difficult balance." (PMID 25071759, 2014). "Various studies indicate that TNF-α has a contradictory role in the tumor development." (PMID 25419573, 2014). "In addition, NF-κB-dependent inflammatory cytokines such as IL-6, TNF-α, and CXCL1/KC have been linked with the enhanced immunosuppressive activity of tumor-infiltrating MDSCs." (PMID 25514597, 2014). "The reported functions of TNF signaling pathway in carcinogenesis include tumor initiation, tumor cell proliferation, tumor angiogenesis, and enhancing the invasive property of tumor cells; therefore, it is not surprising that the TNF signaling pathway is involved in both groups." (PMID 24839399, 2014). "Therefore, the treatment with IFN-γ/TNF-α enabled T-sMs to induce anti-tumor function of the neutrophils by increasing the production and/or release of MPO, NE, and TRAIL, and reducing the expression of Bv8 and Mmp9 genes." (PMID 25587026, 2014). "TNF-α protein is upregulated in the spinal cord at 3 days after tumor cell inoculation." (PMID 24580964, 2014). "For example, a combination of TNF-α, IL-6, and IL-17 may compromise antitumor immunity and, if in sufficient levels throughout the tumor bed, promote tumor progression." (PMID 24955376, 2014). "While tumor rejection was shown to be TNF-dependent and associated with accumulation of MDSC, TNFR2-deficient (TNFR2−/−) mice failed to induce MDSC development upon tumor transplantation and showed impaired tumor growth." (PMID 25400932, 2014). "Our study showed that the less production of intra-tumor TNFα in STZ-diabetic CD8+ T cells-treated mice may lead to insufficient infiltration of tumor-reactive CTLs." (PMID 25390652, 2014). "Interestingly, EC anergy induced by tumor pro-angiogenic factors can be reversed under high dose of TNF-α." (PMID 24734218, 2014). "In a complementing experiment, we found that downregulation of RIPK3 by RNA interference in U-937 and HT-29 cells as two sensitive tumor cell lines that express relatively high levels of RIPK3 significantly blocked TRAIL/zVAD/CHX- as well as TNF/zVAD/CHX-induced necrotic killing." (PMID 24507727, 2014).
tumor (continued). "Here we report that priming with IFN-γ and TNF-α could convert the potential of neutrophils from tumor-promoting to tumor-suppressing." (PMID 25587026, 2014). "In particular, increased adipose tissue creates an oxidative environment that can upregulate the expression of various pro-inflammatory cytokines including TNF-α and IL-6, and this is critically associated with CRC development because these cytokines stimulate tumor growth and progression." (PMID 25515685, 2014). "The suppressive effect of TNF-α inhibition on IR-accelerated tumor growth may be mediated by attenuating TNF-α -dependent inflammation." (PMID 24397824, 2014). "Low-dose TNF-α pretreatment also showed similar effects on tumor growth." (PMID 24397824, 2014). "The decreased proliferation of CD8+ T cells upon co-culture with IL-4- and TNFα-pretreated tumor cells could be partially converted by the use of an anti-B7-H1 blocking antibody as proof for the inhibitory role of B7-H1 on tumor cells." (PMID 24885059, 2014). "Elevated intratumoural TNF-alpha levels were supported by TNF-alpha staining in tumour sections." (PMID 24895598, 2014). "A reduction in TNF-α could lead to a reduction in cytostatic activity of AMs and may promote tumour growth and proliferation." (PMID 26316944, 2014). "In general, TNF-α is normally able to rapidly increase endothelial permeability and decrease interstitial fluid pressure in tumors, both of which are believed to overcome significant barriers to drug penetration into tumor tissues." (PMID 24466321, 2014). "Moreover, these processes are further potentiated by inflammatory cytokines found in the tumor microenvironment, such as TNFα and IL-1β." (PMID 24598028, 2014). "This suggests a novel function for eosinophil-derived TNF in regulating tumor cell growth, and that tumor cells may be directly recognized by eosinophils." (PMID 25426119, 2014). "Previous studies also revealed that TNF-α contributed to tumor progression in a paracrine manner." (PMID 24885636, 2014). "TNFα potentially represents a link between immune factors and glutamate receptor activation as glutamate has been shown to stimulate migration of microglial cells to the tumor." (PMID 25593989, 2014). "We hypothesized that selective blocking of TNFR2/p75 LLCs may sensitize them to TNF-induced apoptosis and affect the tumor growth." (PMID 24664144, 2014). "Stress inhibits the immune response ability in antigen-specific T-cells and natural killer cells while stimulates the secretion of proinflammatory cytokines, such as IL-1, IL-2, IL-6, IL-8, IL-11 and TNF-α, which were regarded as co-factors for modulating the growth and progression of tumor." (PMID 24555849, 2014). "Supporting a mechanism in which WT-Ras has been turned into an active entity, and in line with the fact that the MEK-Erk pathway mediates many of the Ras-induced activities, MEK-dependent pathways were involved in the ability of TNFα to induce CXCL8 expression in WT-Ras-expressing tumor cells." (PMID 24598028, 2014). "Interestingly, the same heterogeneous pattern was found for MGP, GGCX, and VKOR, while OPN and TNFα were found clearly upregulated in tumor samples." (PMID 24949434, 2014). "Indeed, inflammation plays a crucial role in promoting tumor development and metastasis, and there is much evidence to suggest that TNF-α is a key pro-inflammatory cytokine involved in tumorigenesis." (PMID 24397824, 2014). "However, if the neutrophils were pre-treated with IFN-γ or TNF-α, T-sMs increased Rab27a expression in the neutrophils from tumor-bearing mice and pG/pI6-mice to the similar level of that in the neutrophils from naive mice." (PMID 25587026, 2014). "Numerical solutions of a mathematical formalization of the opposing pro-angiogenic and cytotoxic functions of TNF qualitatively reproduce the experimentally observed tumor growth dynamics and lend further support to the therapeutic promise of TNFR2/p75 inhibition." (PMID 24664144, 2014).
tumor (continued). "Previous studies have shown that NF-kB may be involved in promoting tumor metastasis by regulating cytokines such as TNF, IL, MMP-9, and ICAM." (PMID 24837834, 2014). "Then, we determined the mechanisms involved (Ras-binding-domain assays, Western blot, luciferase), and tested the impact of Ras + TNFα on angiogenicity (chorioallantoic membrane assays) and on tumor growth at the mammary fat pad of mice and on metastasis, in vivo." (PMID 24598028, 2014). "Hence, with the current results, we analyzed the effect of BCG instillation during TNF-α treatment of various tumor cell lines." (PMID 25208737, 2014). "We next investigated whether IFN-γ and TNF-α could resume the antitumor potential of the neutrophils from tumor-bearing mice and pG/pI6-mice." (PMID 25587026, 2014). "Our data in this study showed that priming with IFN-γ and TNF-α could convert the function of neutrophils from tumor-promoting to tumor-suppressing." (PMID 25587026, 2014). "To understand the mechanisms of antitumor efficacy induced by hUCMSCs- LV-IL-21, we examined the serum cytokines of IL-21, IFN-γ, and TNF-α, which have an important functions in antitumor immunity and their levels indirectly represent the capacity of rejection of tumor in bearing-tumor nude mice." (PMID 24444073, 2014). "Our data also support the idea that by increasing cell adhesion, TNF-α may encourage separate complex tumour parenchymal-stromal cell interactions, consistent with a pro-tumour activity for TNF-α noted by others." (PMID 24979620, 2014). "Taken together our findings suggest that TNF-α could up-regulate the inflammatory response following IR, and possibly produce a microenvironment that promotes tumor growth." (PMID 24397824, 2014). "In addition, activated Vγ9Vδ2 T cells secrete IFN-γ and TNF-α, which have cytotoxic activity against tumor cells directly and indirectly via stimulating macrophages and DCs." (PMID 25505472, 2014). "Although TNF-α can destroy tumors, in different environments, it may possess other effects, even acting as an endogenous tumor promoter." (PMID 24885472, 2014). "Moreover, CXCL16 also indirectly induces the infiltration of M1 macrophages, which induce tumor cell apoptosis by secreting TNF-α." (PMID 25495942, 2014). "One such cytokine commonly found in the tumor microenvironment is TNF-α." (PMID 25419573, 2014). "Activation of NF-κB signaling due to TNF-α helps tumor cells to escape TNF-α-induced cytotoxicity." (PMID 25419573, 2014). "Moreover, there were significantly fewer perforin-, granzyme B- and TNFα-producing cells in the tumor of mice receiving STZ-diabetic P14 CD8+ effector cells than STZ-non-diabetic group." (PMID 25390652, 2014). "The results indicate that the tested GpEPS (at concentrations above 22.85 μg/mL and 228.5 μg/mL) may exhibit selective activity against tumor cells (cell lines SiHa) and stimulate production of TNF-α THP-1-derived macrophages at the level of 752.17 pg/mL." (PMID 25114920, 2014). "In conclusion, our results demonstrated that TNF-α plays an important role in IR-induced outgrowth of colorectal liver metastases by enhancing inflammatory cell infiltration and the formation of the microenvironment that facilitates tumor progression." (PMID 24397824, 2014). "Inflammatory cytokines such as interleukin-6 (IL-6), tumor necrosis factor alpha (TNF-α), and interleukin-1 beta (IL-1β) produced by the tumor or adipose tissue may also contribute to adipose depletion." (PMID 25415607, 2014). "Interestingly, levels of both IL-6 and TNF-α level was found to be substantially higher in untreated tumor bearing mice." (PMID 24504138, 2014). "Chen and colleagues reported that some anti-inflammatory phytochemicals like EGCG appear to modulate the tumor microenvironment by repressing NF-kappaB (NF-κB, a proinflammatory transcription factor), and inhibiting pro-inflammatory cytokines like IL-6 and TNF-α in epithelial ovarian cancer." (PMID 25175005, 2014).
tumor (continued). "Reovirus-loaded LAKDC, and to a lesser degree iDC, were able to: (i) protect from NAb and hand-off reovirus for tumor cell killing; (ii) induce a proinflammatory cytokine milieu (IFNɣ, IL-12, IFNα and TNFα) and (iii) generate an innate and specific antitumor adaptive immune response." (PMID 23982804, 2014). "Of note, TNF-α-driven apoptosis is one of the known mechanisms of tumor clearance." (PMID 25208737, 2014). "This latter result indicates that following their stimulation by TNFα, RasG12V-expressing cells secreted to the culture medium soluble factors that had pro-cancerous effects that promoted tumor growth, as was previously indicated by our in vitro analyses of CXCL8." (PMID 24598028, 2014). "Moreover, the joint activities of TNFα and activated Ras led to cooperative induction of angiogenesis and to increased dissemination of tumor cells to lymph nodes (LN)." (PMID 24598028, 2014). "M1 macrophages produce TNF-α, which has cytotoxic activity against tumor cells." (PMID 25495942, 2014). "It is reported that increased endogenous TNF-α may promote tumor invasion via downregulating the PR expression in BC." (PMID 24864130, 2014). "Furthermore, in an experimental murine cancer metastasis model in which tumor growth was stimulated by bacterial lipopolysaccharide (LPS) injection, TNF-α-induced NF-κB signaling in tumor cells was essential for the generation of metastasis." (PMID 24901008, 2014). "In contrast, low, sustained TNF-α production levels can induce a tumor phenotype." (PMID 24901008, 2014). "Low adiponectin levels are potentially associated with carcinogenesis, indirectly through its effects on TNF-α and tumor cell proliferation and directly by its effects on the regulation of hematopoiesis and system, selective binding to several mitogenic growth factors, and inhibition of NF-κB." (PMID 24829560, 2014). "The higher proliferation of M-406 cells observed when cultured with CMO from both Naïve CBi/L and CBi mice indicates that these media would contain factor/s like IL-2, IL-4, INF-γ, IL-10, TNF-α and many others, yet to be identified, capable to stimulate or inhibit tumor growth." (PMID 24885995, 2014). "In addition, TNF-α, an essential factor in tumor progression and metastasis, significantly enhanced the release of ATP, especially in MDA-MB-231." (PMID 25156554, 2014). "Our findings further demonstrate that TNFα transforms WT-Ras into a tumor-promoting entity." (PMID 24598028, 2014). "Some cytokines, such as TNF-α, have anti-tumor effects and could be of benefit for tumor suppression after BMT." (PMID 24847950, 2014). "Furthermore, TNF-α can directly affect tumor cells by increasing lysosomal enzymes and inducing cytochrome c release from the mitochondria and apoptosis." (PMID 25548907, 2014). "In addition, mice with Bacteroides vulgatus or dual knockout mice (Il10- and MyD88-deficient mice) treated with AOM showed reduced transcription of Il12p40 and TNF-α and remained tumor-free." (PMID 25076949, 2014). "TNF-α is intensively produced by tumor cells in advanced cancer and it may suppress adiponectin expression in adipose tissue." (PMID 25049439, 2014). "Those who recovered from their disease were found to have a measurable EBV DNA load, together with a high frequency of IFN-γ and TNF-α producing PBMCs (p = 0.04), which indicates the existence of a Th1-type polarized immune response in both the tumor and its surrounding tissue." (PMID 25213133, 2014). "However, activation of the NF-κB pathway through the receptor-interaction protein upon binding of TNF facilitates cell survival and proliferation, which will decrease the anti-tumor apoptotic properties of TNF." (PMID 23635099, 2013).
tumor (continued). "Additionally, the level of tumor-induced TNF-α decreased in the group treated with the combined nutrients, which pretty much agrees with previous investigations." (PMID 23349693, 2013). "PAX3-and PAX7-FKHR gene fusion, mutations in the von Hippel Lindau gene, hypoxic conditions in the tumor microenvironment, NF-κB, vascular endothelial growth factor, and tumor necrosis factor alpha have all been found to regulate CXCR4 overexpression in different tumor cells." (PMID 23472074, 2013). "Of note, endogenous tumor-produced TNF can have a remarkable protumorigenic activity, for instance by inducing expression of interleukin 13 receptor alpha 2 (IL13Rα2) on tumor resident monocytic cells and the subsequent production of the immunosuppressive cytokine TGF-beta." (PMID 23840967, 2013). "Importantly, therapeutic mechanism of antitumor immunity mediated by RdB/IL23/p35 is associated with the generation and recruitment of IFN-γ- and TNF-α-co-producing T cells in tumor microenvironment." (PMID 23844018, 2013). "However, the microenvironment also consists of low levels of pro-inflammatory cytokines (e.g., IL-1β, TNFα) which paradoxically enhance tumor angiogenesis and proliferation." (PMID 23874303, 2013). "Human tumor-infiltrating Th17 cells have been reported to produce high levels of TNFα and IFNγ." (PMID 24454480, 2013). "TNF is key to natural killer cell-mediated destruction of tumor cells in mice." (PMID 24225257, 2013). "In our study, NO and TNF-α in the CSF exhibited an additive effect in tumor cell cytotoxicity." (PMID 23964349, 2013). "Importantly, intraperitoneal application of TNFα decoy receptor etanercept relieved mice from tumor-mediated hyperalgesia." (PMID 24067145, 2013). "Depending on TNF signaling pathway it may favor tumor growth and differentiation of MDSC or may induce immune responses." (PMID 23394575, 2013). "Multiple mechanisms were proposed to contribute to this synergy, including CXCL10-mediated recruitment of activated T and NK lymphocytes to the tumor, inhibition of tumor angiogenesis by CXCL10, and TNF-alpha-mediated tumor necrosis and maturation of dendritic cells." (PMID 24202446, 2013). "During later stages, tumor growth may be induced by upregulation of pERK and TNFα, although these mechanisms need further study." (PMID 24260500, 2013). "TNFα is an important activator of acute inflammation that appears to play a complex and dual role in cancer, but has at higher doses been shown to have anti-tumor activity." (PMID 24058644, 2013). "CD8, TGF-β, TNF-α and NF-κB participated in the processes of tumor transformation and progression." (PMID 23833665, 2013). "Although TNF has been reported to have anticancer properties, it has been suggested that TNF may also promote cancer development and progression through cellular transformation, tumor promotion, proliferation, invasion, angiogenesis, and metastasis." (PMID 24225257, 2013). "Indeed, FasL or TNFα should first interact with their specific receptors which in turn lead to programmed cell death of tumor targets." (PMID 23667543, 2013). "Thus, egcSEs produced by S. aureus induce NO synthase and the increased NO formation together with TNF-α appear to contribute to egcSE-mediated apoptosis against a broad panel of human tumor cells." (PMID 23964349, 2013). "Vγ9Vδ2T cells interact with and kill tumor targets thorugh several different mechanisms including granule exocytosis, death receptor/ligands interactions with TNF, TRAIL and FasL, and TCR- or NKG2D-mediated recognition of phosphoantigens or stress-inducible molecules, respectively." (PMID 23762301, 2013). "Studies have shown that TNFα has a role in executing either pro- or anti-tumor activities." (PMID 23965971, 2013).